IL6 (interleukin 6)
Diseases named in the same sentence as IL6 in open-access papers (continued):
Sharing a sentence is not in itself a finding about the gene and the disease.
preeclampsia (continued). "High levels of IL-6 can damage vascular endothelial cells, increase vascular permeability, interfere with vasoconstriction and relaxation, and lead to an increase in blood pressure, eventually leads to a series of clinical manifestations of preeclampsia." (PMID 35784937, 2022). "Likewise, two other systematic reviews also identified elevated levels of TNF-α, IL-6, and IL-10 in studies on preeclampsia." (PMID 36034841, 2022). "We previously reported enhanced decidual IL-6 and IL-11 levels at the maternal-fetal interface with significantly higher peri-membranous IL-6 immunostaining in adjacent interstitial trophoblasts in preeclampsia (PE) vs. gestational age (GA)-matched controls." (PMID 35837332, 2022). "Therefore, we evaluated the effects of PDMSCs-CM administration on maternal blood pressure, proteinuria, fetal outcome, and placental expression of sFlt-1, TNF-α, and IL-6 in an LPS-induced mouse model of preeclampsia." (PMID 35163594, 2022). "From our literature search, there are some data indicating that IL-8, IL-12, and IL-6 may be early predictors for the onset of preeclampsia, but more research would be required to confirm these existing findings." (PMID 33680514, 2021). "We also tested if neutrophil–endothelial interaction influenced IL-6, and its soluble receptor production, and whether neutrophil production of IL-6 can be induced by placental factors in preeclampsia." (PMID 35366257, 2021). "Maternal IL-6 and sgp130 are increased in women with preeclampsia." (PMID 35366257, 2021). "Nonetheless, most evidence suggests that IL-8 and IL-6 are higher in preeclampsia compared to healthy pregnant women and may be as a result of preeclampsia." (PMID 33680514, 2021). "IL-6, in fact, has been found significantly higher in smokers’ preterm preeclampsia (PPE) compared to non-smokers’ PPE, underlying a possible contribution of tobacco smoking in enhanced inflammation." (PMID 34884952, 2021). "However, little is known about differences in IL-6, sIL-6R, and sgp130 production by neutrophils and endothelial cells between normal pregnancy and preeclampsia." (PMID 35366257, 2021). "We also found that increased IL-6 and sgp130 levels are associated with reduced suppressor of cytokine signaling-3 (SOCS-3) expression in both maternal vessel endothelium and circulating neutrophils in preeclampsia." (PMID 35366257, 2021). "However, levels of TNF alpha, IL-6, IL-8 and IL-10 in premature infants were found to be unaffected by the mother’s preeclampsia condition." (PMID 32063926, 2020). "IL6 is associated with reduced TGFB output and IL2-mediated STAT5 signaling, and is a possible candidate contributing to impaired Treg capacity in preeclampsia, given that elevated expression of IL6 is seen in gestational tissues of women who later develop the condition." (PMID 30984163, 2019). "Furthermore, high concentrations of TNF-alpha, IFN-gamma, and IL-6 have been measured in the amniotic fluid of mothers undergoing spontaneous miscarriage, preterm delivery, and preeclampsia." (PMID 31790466, 2019). "The effect of MgSO4 on IL-6 secretion has been formerly studied in the context of preeclampsia." (PMID 28243294, 2016). "DBMSCs may use these cytokines to mediate their immunosuppressive functions as it has been recently reported that DBMSCs ameliorate T helper 1 cell induced preeclampsia-like symptoms in mice via the secretion of IL-6, VEGF, and TGF-β." (PMID 27087815, 2016). "In preeclampsia, the ischemic placenta may contribute to the maternal endothelial cell dysfunction by enhancing the synthesis of IL6, TNF α and IL8." (PMID 26113950, 2015). "Furthermore, IL-6 and IP-10 have been shown to be highly expressed in the maternal serum of preeclampsia compared with control specimens." (PMID 24659862, 2014).
preeclampsia (continued). "In our study, women with preeclampsia had a 20-fold increase in serum sEng and sFlt-1 and approximately a twofold increase in markers of neutrophil activation (α-defensins and calprotectin) and the pro-inflammatory cytokine, IL-6." (PMID 22398973, 2012). "However, there was no meaningful relationship between the increase in sEng or sFlt-1 and neutrophil activation, as determined by α-defensins or calprotectin and IL-6 release, in severe preeclampsia." (PMID 22398973, 2012). "We have also examined whether the temporal changes in plasma TNF-alpha and IL-6 levels from the antepartum to the postpartum period correlate with the regression of preeclampsia." (PMID 21253506, 2010). "Our findings support the hypothesis that immune activation is involved in preeclampsia and that IL-6 may participate in the abnormal immune response." (PMID 16259641, 2005). "IL-6 can also stimulate platelet-derived growth factor, a process seen in preeclampsia." (PMID 16259641, 2005). "A positive correlation was observed between IL-6, hsCRP, and sPD-L1, which may be explained as an attempt to stimulate the expression of PD-1/PD-L1 by the ongoing inflammation present in preeclampsia due to immunological dysregulation and imbalance between PD-1/PD-L1 and Tregs/Th17 ratio." (PMID 39328700, 2024). "The purpose of the study was to determine if neutrophils and endothelial cells are sources of IL-6 and its soluble receptors in pregnancy and to test our hypothesis of aberrant IL-6, sIL-6R, and sgp130 production by neutrophils and endothelial cells in preeclampsia." (PMID 35366257, 2021). "Therefore, increased maternal IL-6 and sgp130 levels may reflect suppression of endogenous anti-inflammatory activity in endothelial cells and neutrophils in preeclampsia." (PMID 35366257, 2021). "Moreover, elevated levels of both TNFα and IL-6 were identified in women with preeclampsia." (PMID 31186952, 2019). "Additionally, we sought to determine whether the disordered angiogenesis markers sFlt-1, PlGF, and PlGF as well as the sFlt-1/PlGF ratio correlate with the inflammatory markers hsCRP and IL-6 in early or late preeclampsia patients and in IUGR patients." (PMID 27760191, 2016). "The aim was to assess whether disordered angiogenesis markers sFlt-1, PlGF, and the sFlt-1/PlGF ratio and inflammatory markers hsCRP and IL-6 differed between the study group and the control group, and among study subgroups (early and late preeclampsia and IUGR)." (PMID 27760191, 2016). "The study was undertaken in women with established preeclampsia and it is not possible to determine whether the increased concentration of IL-6 is a cause or consequence of the disease." (PMID 16259641, 2005). "After FMT in mice treated with antibiotics, we found that the levels of serum LPS, IL-6, and TNF-α in the group of mice transplanted with fecal microbiota fluid from patients with preeclampsia were higher than those in the other three groups." (PMID 40832058, 2025). "In preeclampsia, there is an increase in the level of pro-inflammatory cytokines such as TNF, IL-6, and IL-17, which contributes to the development of cytotoxic inflammation." (PMID 40647643, 2025). "Within the placebo group, IL-6, sTNF-R1 and sTNF-R2 mean concentrations were higher in preeclampsia at 34–38 weeks (FDR < 0.05) and PLGF mean concentrations were lower in preeclampsia at 24–28 and 34–28 weeks (FDR < 0.05)." (PMID 38851168, 2024). "The overexpression of circulating IL-6, IL-8, IL-1β and tumour necrosis factor-alpha (TNF-α) in cases of preeclampsia maintain a chronic pro-inflammatory state." (PMID 39124698, 2024). "Studies have consistently reported elevated levels of various cytokines in preeclampsia, including PGE2, TNF-α, IL-1, IL-6, and CRP." (PMID 38672972, 2024). "Preeclampsia is a state of chronic inflammation with an immune imbalance where proinflammatory cytokines are increased (TNF-α, IL-6, IL-17) and anti-inflammatory cytokines are reduced (IL-10, IL-4)." (PMID 37887854, 2023).
preeclampsia (continued). "Inflammatory markers such as tumor necrosis factor-α (TNF-α) and Interleukin-6 (IL-6) are elevated in GDM and preeclampsia." (PMID 37764061, 2023). "In a study using a rat model of preeclampsia, reduced placental blood flow (RUPP-model) led to oxidative stress and increased proinflammatory cytokines like IL-6, IL-17, and TNFα." (PMID 37893042, 2023). "Irisin also decreases systolic and diastolic blood pressures, ET-1, IL-6, and MDA and increases SOD, PGF, and NO levels in mothers with preeclampsia in the third trimester." (PMID 37964253, 2023). "In addition, the study found increased levels of IL-6 and IL-8 in the blood of patients with preeclampsia compared to women with normal pregnancies, supporting the hypothesis of an increased inflammatory response in preeclampsia." (PMID 36700203, 2022). "Compared with healthy group, the levels of serum Lp-PLA2, CRP, IL-6 and TNF-α in gestational hypertension group, mild preeclampsia group and severe preeclampsia group all increased." (PMID 35784937, 2022). "Inflammatory markers such as cytokines (IL-1b, IL-6, TNF-α, INF-γ) are involved in the pathogenesis of preeclampsia." (PMID 33809556, 2021). "Inflammatory markers (IL-6, IL-8 and TNF-alpha) were increased in the CSF of women with eclampsia, compared to those with preeclampsia and women with normotensive pregnancies." (PMID 34831266, 2021). "Women with eclampsia (n = 4) showed increased CSF concentrations of all pro-inflammatory cytokines and TNF-alpha compared to women with normotensive pregnancies (n = 7) and also for interleukin-6 and TNF-alpha compared to women with preeclampsia (n = 4)." (PMID 34831266, 2021). "Plasma levels of interleukin-6 (IL-6) and tumor necrosis factor-α (TNF-α) have been shown to be elevated in preeclampsia." (PMID 34045549, 2021). "This study showed that L-NAME promoted significant increases in mean BP, total urine protein level, urea, creatinine, ET-1, IL-6, and MDA (p < 0.001), but decreased serum NO level (p < 0.001) in the preeclampsia group when compared to normal pregnant group." (PMID 33850656, 2021). "Lymphocyte T cells can significantly increase the production of inflammatory cytokines such as tumor necrosis factor alpha (TNFα) and interleukin-6 (IL6), as shown in preeclampsia." (PMID 32116801, 2020). "In a lipopolysaccharide (LPS)-induced preeclampsia rat model, UC-MSC transplantation improved preeclampsia symptoms and reduced the levels of inflammatory cytokines such as TNF-α and IL-6." (PMID 33050021, 2020). "This is in agreement with recent studies of maternal inflammation (cytokines such as IL-6, TNF-α) in preeclampsia, whereby low level inflammation is evident early in pregnancies but is amplified in the third trimester of pregnancy." (PMID 30976066, 2019). "In vitro, MenSCs obtained from patients with a history of preeclampsia expressed less endoglin and secreted less VEGF but more IL-6 than controls did." (PMID 30809262, 2019). "Although metformin reduced the levels of interleukin-6 (IL-6) and C-reactive protein (CRP), which are commonly elevated in preeclampsia cases, the incidence of pre-eclampsia was similar in both arms of the EMPOWaR study." (PMID 29082364, 2017). "The inflammatory markers, IL6, TNF α and CRP were significantly higher in the group with severe preeclampsia." (PMID 26113950, 2015). "In preeclampsia, the pro-inflammatory TNF-α and IL-6 and C-reactive protein are higher compared to normal pregnancy." (PMID 26247971, 2015). "This study reports increased levels of the inflammatory cytokines, IL6, TNF α and the marker of inflammation, CRP in severe preeclampsia." (PMID 26113950, 2015). "In particular, IL-6 and TNF-α are important players contributing to the endothelial dysfunction observed in preeclampsia." (PMID 26247971, 2015). "ELISA further showed that serum concentrations of IL-6 and MCP-1 in severe preeclampsia significantly exceeded those of normal pregnancy." (PMID 25853857, 2015).
preeclampsia (continued). "Other models for preeclampsia, TNF infusion or IL-6 infusion in pregnant Sprague-Dawley rats did show decreased total vascular reactivity in the aorta as compared with control rats." (PMID 24223202, 2013). "On the contrary, others did not manage to identify a correlation between maternal serum levels of IL-6 or TNF-alpha and preeclampsia." (PMID 21253506, 2010). "Maternal serum levels of IL-6 and TNF-alpha play a significant role in pathogenesis of preeclampsia." (PMID 21253506, 2010). "Next, we observed that a history of early-onset preeclampsia is related to higher plasma levels of CRP, fibrinogen and IL-6 at least six months after delivery." (PMID 18382655, 2008). "We cannot determine whether IL-6 is an active mediator in preeclampsia or a marker of immune activation, and it seems necessary to perform further studies, including longitudinal studies before the onset of preeclampsia, to elucidate the role of this cytokine in the pathogenesis of preeclampsia." (PMID 16259641, 2005). "Women with preeclampsia had significantly higher levels of CRP, IL-4, IL-6, IL-8, IL-10, and TNF-α." (PMID 41346429, 2025). "The interconnection of autonomic failure with elevated circulating cytokines, such as IL-6, TNF-α, could further disrupt homeostatic cardiovascular responses, amplifying risks such as severe orthostatic hypotension or preeclampsia." (PMID 40244235, 2025). "IL-6, CRP and TNF-α in females with preeclampsia were elevated in comparison to the controls." (PMID 41394354, 2025). "In addition, the circulating levels of pro-inflammatory cytokines, such as IL-6, TNF-α, and chemokines IL-8, IP-10 (interferon-gamma-induced protein 10) and MCP-1 (monocyte chemoattractant protein 1) are elevated in preeclampsia." (PMID 41346429, 2025). "The inflammatory markers IL-6 and hsCRP were both raised significantly in preeclampsia cases compared to normal non-pregnant and normal pregnancy participants." (PMID 39328700, 2024). "Expression levels of chemerin, IL-6, and TNF-α are increased in gestational diabetes, and the increases in chemerin in late pregnancy positively correlate with the ratio of sFlt-1 to PlGF as a marker of preeclampsia." (PMID 37964253, 2023). "The IL-6/STAT3 signaling pathway could be repressed by pravastatin to alleviate oxidative stress, improve preeclampsia, and decrease the apoptosis of placental trophoblastic cells in rats with PE39." (PMID 37828060, 2023). "Regarding IL-6, we found that the levels were higher in preeclampsia when compared with normal pregnant women (p = 0.01) and normal non-pregnant women (p = 0.048)." (PMID 37700972, 2023). "Hence, in obese women with preeclampsia, the concentration of adiponectin decreases, and the concentrations of TNF-α, CRP, and IL-6 plasma increase." (PMID 37964253, 2023). "In this study, the overall CSF concentrations of IL-6 were higher than in our study but not different between preeclampsia and normotensive women." (PMID 34831266, 2021). "Women with preeclampsia also showed increases in pro-inflammatory cytokines IL-6 and IL-8 but not TNF-alpha in the CSF compared to women with normotensive pregnancies." (PMID 34831266, 2021). "For instance, in the plasma of mothers with preeclampsia, concentrations of IL-6, but not TNFα or IL-1β, were higher than those reported in normal patients." (PMID 34696359, 2021). "Levels of TNF-α, IL-1β, and IL-6 were increased but IL-10 was decreased in culture medium of monocytes from women with preeclampsia compared with those from nonpregnant and normotensive pregnant women (all p < 0.01)." (PMID 31138166, 2019). "In addition, circulating levels of IL6, tumor necrosis factor alpha (TNFα) and monocyte chemoattractant protein 1 (MCP-1) have been found to be elevated in preeclampsia." (PMID 29145462, 2017). "The inflammatory cytokines, IL6, TNF α and CRP are elevated in severe preeclampsia and may mediate some of the clinical manifestations of the disorder." (PMID 26113950, 2015).
preeclampsia (continued). "As a result of these controversies, we decided to measure the serum concentrations of IL-6, TNF α, and C reactive protein (CRP) in women with severe preeclampsia, and to determine if they differ from those of gestational age matched, normotensive, pregnant women." (PMID 26113950, 2015). "In addition, both IL-6 and MCP-1 mRNA levels of severe preeclampsia placenta were significantly higher than those of the control." (PMID 25853857, 2015). "Circulating levels of the pro-inflammatory cytokines IL-6 and TNF-α, the chemokines IL-8, IP-10 and MCP-1, as well as the adhesion molecules ICAM-1 and VCAM-1, were raised in preeclampsia compared with healthy pregnancy, resulting in an overall pro-inflammatory systemic environment." (PMID 21126355, 2010). "According to our results, only the circulating levels of TNF-alpha and not those of IL-6 were enhanced in women with preeclampsia when compared to normotensive women." (PMID 21253506, 2010). "Apart from the two stimulation variants reflecting a preeclampsia-like environment (PLE1: 2%O2 + 1 ng/mL IL6 + 10 μM H2O2 and PLE2: 2%O2 + 10 ng/mL IL6 + 50 μM H2O2), no significant changes in CHGA gene expression were obtained in the HTR-8/SVneo and BeWO cell lines compared to controls." (PMID 37108287, 2023). "However, the specific role of IL-6-regulated ferroptosis in preeclampsia has not been reported and needs to be further explored." (PMID 36061193, 2022). "TGF-β1 level in maternal serum is increased in preeclampsia; the phagocytosis by endothelial cells of necrotic trophoblast released in maternal circulation leads to TGF-β1 secretion, which increases interleukin 6 (IL-6) expression, and then IL-6 induces activation of endothelial cells." (PMID 33673360, 2021). "This study is to determine the concentrations of IL-6, TNF α, and C reactive protein (CRP) in women with severe preeclampsia, and compare with those of gestational age- matched normotensive pregnant women and to correlate CRP levels with markers of organ damage in women with preeclampsia." (PMID 26113950, 2015). "Because sgp130 binds to sIL-6R/IL-6 and blocks sIL-6R/IL-6 trans-signaling-induced endogenous anti-inflammatory activity in endothelial cells (such as SOCS-3 induction), increased sgp130 production could be considered an indicator of reduced anti-inflammatory activity in preeclampsia." (PMID 35366257, 2021). "Our results showing no changes of maternal circulating TNF-alpha and a drop, but not a significant one, of IL-6 levels long after delivery suggest that the source of the excessive production of TNF-alpha in preeclampsia may be monocytes, neutrophils, and unlikely placenta itself." (PMID 21253506, 2010). "Furthermore, there is no information about maternal blood concentrations of IL-6 and TNF-alpha in women with preeclampsia long time after delivery." (PMID 21253506, 2010).